AQP5 (aquaporin 5)
Diseases named in the same sentence as AQP5 in open-access papers (continued):
Sharing a sentence is not in itself a finding about the gene and the disease.
tumor (continued). "Early studies suggest that AQP5 may influence tumor behavior and patient prognosis, but further research is needed to clarify the broader role of AQPs and their potential as therapeutic targets in GBC." (PMID 39596202, 2024). "Increased expression of AQP5 in prostate cancer was linked to the stage of the tumour node metastasis and lymph node metastasis." (PMID 38336645, 2024). "In a recent study, it was proposed that phosphorylation of AQP5 at Ser156, followed by its interaction with c-Src, could enhance the invasive capacity of tumor cells." (PMID 39440058, 2024). "AQP5 correlated positively with the tumour-node-metastasis stage of NSCLC." (PMID 38336645, 2024). "Therefore, the elevation of AQP3 and AQP5 expression proves advantageous in augmenting the aggressiveness of tumor cells." (PMID 39440058, 2024). "In clinical conditions, upregulation of AQP5 is a sign of poor prognosis in neoplastic diseases." (PMID 36766810, 2023). "According to our current study, the expression of AQP5 was related to the location of the tumor which might remind us that AQP5 played a different role in left and right-sided CRC." (PMID 37334171, 2023). "In such cancer, Aqp5 silencing inhibited the WNT/β-catenin signaling, increased the chemosensitivity to chemotherapy-inducing apoptosis, and suppressed tumor growth, suggesting AQP5 could be a useful therapeutic target for such cancer." (PMID 36768212, 2023). "In addition, Aqp5 gene promoter methylation varies according to the type of tumor, with lower methylation and higher gene expression in basal tumors as compared to luminal tumors." (PMID 36768212, 2023). "Many studies point to the potential usefulness of AQP5 as a biomarker of neoplasms." (PMID 36766810, 2023). "The strong AQP5 expression was positively correlated with tumor grade in BCs (p<0.001)." (PMID 36706090, 2023). "Moreover, multivariate regression analysis demonstrated that AQP5 expression was positively correlated with tumor grade (p = 0.012) in GCs." (PMID 36372898, 2022). "AQP3, a member of the AQP5 homoprotein family, has been proven to promote tumor development by activating autophagy, which prompted us to hypothesize that AQP5 might regulate autophagy to determine the fates of GC-CSCs." (PMID 36372898, 2022). "Furthermore, we used the TIMER web resource and the TISIDB database to analyze the correlation between AQP5 and tumor-infiltrated immune cells in the PAAD microenvironment." (PMID 35619903, 2022). "In addition, we used the TIMER database to investigate the relationship between AQP5 expression and the gene markers of tumor-infiltrating immune cells in PAAD." (PMID 35619903, 2022). "Although CD4+ and CD8+ Tcm can inhibit tumor progression, we also found that AQP5 expression might reduce CD4+ Tem in our study." (PMID 35619903, 2022). "Thus, the results consistently point to the notion that the AQP5 + cell compartment is an important tumor-initiating population." (PMID 36372898, 2022). "Specifically, AQP5 has been shown to be associated with the development especially metastasis of CRC, Thus, silencing of AQPs may act as a novel class of anti-tumor agents." (PMID 36114463, 2022). "Although the mechanism responsible for the slight difference in effects between MSC-derived exosomes and MSC’s conditioned media is unclear, this study clarified that exosomes act against tumor development through reducing the expression of AQP5 and EGFR cell surface receptors." (PMID 36114463, 2022). "Moreover, expression of AQP1, AQP3, and AQP5 was found among tumor-infiltrating lymphocytes surrounding bronchogenic carcinoma cells." (PMID 35847914, 2022). "Chae and colleagues reported that AQP5 promoted tumor invasion in NSCLC." (PMID 33924231, 2021). "Blocking AQP5 expression reduced cell migration of this tumor." (PMID 33271827, 2020). "There is much evidence suggesting the importance of AQP5 upregulation in tumor cell proliferation." (PMID 31623386, 2019).
tumor (continued). "In addition, AQP5 gene silencing inhibits the proliferation of endometrial glandular epithelial cells notably, suggesting that altered AQP5 expression plays a crucial role in tumor progression." (PMID 28404978, 2017). "While an initial acute stress induces cell sensitivity, under chronic stress conditions similar to tumor cell niches, AQP5 may facilitate metabolic adaptation, cell survival, and resistance." (PMID 27983600, 2016). "The fact that AQP5 was found preferentially phosphorylated in tumor cells strongly suggests that its regulation might be involved in tumorigenesis." (PMID 27983600, 2016). "Besides, co-expression of AQP3 and AQP5 in HCCs has a significant association with serum AFP and tumor stage and grade." (PMID 25886458, 2015). "However, the tumor cells within the ovary would still require a higher level of AQP5 for proliferation and migration." (PMID 25344048, 2014). "Moreover, intensive studies have been focused on the modulation of AQP5 expression in tumor cells and its effects on tumorigenesis, tumor growth and progression." (PMID 25217331, 2014). "AQP5-ir cells were also found in flattened cells surrounding tumor nodules." (PMID 25344048, 2014). "The effects of down-regulating AQP5 on tumorigenesis were tested by tumor xenografts experiments." (PMID 25298246, 2014). "In addition, the frequencies of aberrant AQP5 expression were higher in HCC tissues with higher tumor stage (T3~4) than those with lower tumor stage (P = 0.008)." (PMID 24224160, 2013). "In conclusion, our data suggest for the first time that the aberrant expression of AQP3 and AQP5 proteins may be strongly related to tumor progression and prognosis in patients with HCC." (PMID 24224160, 2013). "Moreover, combined AQP3 and AQP5 protein expression was significantly associated with serum AFP (P = 0.008), tumor stage (P = 0.006), and tumor grade (P = 0.006)." (PMID 24224160, 2013). "Recent studies have showed the altered expression of AQP3 and AQP5 in various tumor types." (PMID 24224160, 2013). "In addition, combined AQP3 and AQP5 protein expression was significantly associated with serum AFP (P = 0.008), tumor stage (P = 0.006), and tumor grade (P = 0.006)." (PMID 24224160, 2013). "Importantly, semi-quantitative measurement of AQP5 labeling intensity demonstrated that AQP5 labeling intensity was more prominent in the invasive tumor cells when LNs were involved." (PMID 22145049, 2011). "Cell culture experiments also revealed the role of AQP5 in tumor cell proliferation and migration." (PMID 22145049, 2011). "Moreover, the approximate numbers of AQP5-positive tumor cells among the total tumor cells were increased." (PMID 22145049, 2011). "From our clinical findings, we have hypothesized that AQP5 may induce cell invasion, a necessary step for tumor metastasis." (PMID 18478076, 2008). "However, no other statistically significant correlation was found in NSCLCs between AQP5 expression and demographic and pathologic factors, such as age, sex, histological differentiation, and tumor stage." (PMID 18478076, 2008). "Interestingly, the expression of human AQP1, AQP3, and AQP5 was detected in tumor-infiltrating lymphocytes surrounding bronchogenic cancer of lung." (PMID 18612408, 2008). "Interestingly, athymic mice injected with NIH3T3 cells stably transfected with AQP5 exhibited a robust tumor formation." (PMID 18612408, 2008). "In addition, AQP5 expression has been related to PDAC tumor differentiation." (PMID 40379788, 2025). "Aqp5-induced changes in tumor biological behavior may be regulated by a variety of signaling pathways leading to cell transformation, including tyrosine kinase Src family, epidermal growth factor receptor, Wnt signaling pathway and Erk1/2 mediated signal transduction." (PMID 40760228, 2025).
tumor (continued). "In the same study, AQP3 and AQP5 were associated with increased levels of EGFR, proliferation marker Ki-67, cytokeratin 7 and vimentin, while E-cadherin was found to be decreased, indicating the contribution of these AQP isoforms to EMT, tumor growth and invasion." (PMID 39941100, 2025). "In addition, AQP5 was phosphorylated on Ser156 in tumor cells." (PMID 36768212, 2023). "In addition, in PAAD samples, AQP5 was overexpressed in the apical membrane of intercalated cells and was related to tumor differentiation, suggesting that it may play a role in cancer progression." (PMID 35619903, 2022). "However, the association between Aquaporin-5 (AQP5) expression and prognosis and tumor-infiltrating lymphocytes in PAAD has not been reported." (PMID 35619903, 2022). "Interestingly, AQP5 is a potential epigenetic driver of tumor development." (PMID 33959500, 2021). "AQP5 also may be involved in cell proliferation, differentiation, migration, and invasion of tumor." (PMID 32053992, 2020). "Therefore, these outcomes imply that accumulation of elevated AQP5 protein and mRNA may result in tumorigenesis and tumor progression." (PMID 29678898, 2018). "Besides translocation to the plasma membrane, phosphorylation of AQP5 was shown to promote cell proliferation and, interestingly, AQP5 Ser156 was found preferentially phosphorylated in tumor cells, supporting AQP5 phosphorylation involvement in cell proliferation." (PMID 27983600, 2016). "Furthermore, interfering of AQP5 during tumorigenesis could efficiently decrease the tumor growth in athymic mice." (PMID 25298246, 2014). "Eleven potential tumor targets were identified, including CEACAM5, TMPRSS4, COL17A1, CLDN18, and AQP5." (PMID 40379788, 2025). "Its high expression in aquaporin 5+ (AQP5) CSCs maintains cell stemness by regulating histone methylation, thereby promoting malignant tumor progression." (PMID 41159730, 2025). "However, the specific mechanism by which AQP5 promotes tumor development remains unclear." (PMID 40760228, 2025). "They identified AQP5, KiSS-1, FZD7, AURKB, UBE2C, and PTTG1 as overexpressed in recurrent CNs, suggesting these genes play a role in tumor progression." (PMID 39066950, 2024). "However, a paper published in 2021 demonstrated that a higher expression of AQP5 correlates with longer survival time (OS) and that high AQP5 expression is associated with a large number of infiltrating B lymphocytes and CD4+ lymphocytes, that is, TILs (tumor infiltrating lymphocytes)." (PMID 36766810, 2023). "However, the association between tumor size and age with AQP5 expression was not noteworthy." (PMID 36672280, 2023). "Further experiments are needed to explore the mechanisms of AQP5 in PAAD and its interactions with tumor immunity using in vitro and in vivo models." (PMID 35619903, 2022). "In this study, we aimed to investigate the effects of adipose-derived mesenchymal stem cells secreted exosomes on the expression of aquaporin 5 and EGFR genes in the HCT-116 tumor cell line." (PMID 36114463, 2022). "By integrating these data, the expression of AQP5 and AQP6 was found to be significantly lower in tumor tissues but inapparent to clinical stage and pathological grade." (PMID 36254092, 2022). "The squamoid cells (CK5+, CK8+) and the mucin-producing cells (CK8+, AQP5+, MUC4+) comprised the tumor mass in both PDOs and the parental tumors, and these cells formed typical luminal structure and nest patterns." (PMID 36527158, 2022). "In both organoids and tumor tissues, CK8+ AQP5+ cells were the major population, which suggested that the tumor cells in SDC were terminally differentiated ductal cells." (PMID 36527158, 2022). "In the TCGA-HNSC cohort, we observed the expression of 12 ion channel genes in tumor and normal tissues; ANO1, AQP9, BEST2, CHRNA5, and KCNJ15 were upregulated in HNSCC, while AQP1, AQP5, SCNN1G, and SCN4A were downregulated." (PMID 36389709, 2022).
tumor (continued). "At the same time, the abnormal expression of AQP5 can regulate the EGFR pathway and promote the proliferation of tumor cells." (PMID 35245343, 2022). "Overall, these results indicated that AQP3 and AQP5 are involved in the development of several tumor types, especially in HCC, but the two proteins function as tumor promoter or tumor suppressor in different tumor types." (PMID 24224160, 2013). "The modulation of these genes’ expression was analyzed, according to the age range and gender of the patients and the grade of tumor invasiveness and aggressiveness, and was further correlated with the gene expression of AQP1, AQP3, AQP5, and AQP9, previously reported." (PMID 40305202, 2025). "In addition, the coexpression of the AQP3 and AQP5 proteins is positively correlated with elevated serum AFP levels, tumor stage, and tumor grade." (PMID 39048663, 2024). "The genetic relationship between AQP5 and any known type of neoplasm has not been completely identified." (PMID 36766810, 2023). "Almost no tumor cell was identified as acinar cells, in accordance with the scarce expression of acinar genes (e.g., AQP5, NKCC1, AMY1A)." (PMID 35860547, 2022). "On the basis of our pan-cancer analysis, in LGG and SKCM, the high expression of AQP5 was related to worse OS and DSS, which is consistent with the hypothesis that AQP5 may promote the proliferation and metastasis of tumor cells." (PMID 33343628, 2020). "The relationships between age or tumor size with the expression of AQP5 were not significant (P > 0.05)." (PMID 25217331, 2014). "Although the role of AQP3 and AQP5 in human tumor pathology has been explored extensively, their molecular mechanisms in different tumor types have not been fully elucidated." (PMID 24224160, 2013). "Cases with AQP5-positive status (IHC-score: ≥2) displayed a higher rate of tumor recurrence than negative ones in NSCLC (54.7% vs. 35.1%, p = 0.005) and worse disease-free survival (p = 0.033; OR = 1.52; 95%CI:1.04−2.23)." (PMID 18478076, 2008). "While we found AQP5 expression in cancer cells, we did not see any evidence of AQP5 immunoreactivity among tumor-infiltrating lymphocytes, which is contrary to our previous findings showing an induced expression of AQP5 messages during lymphocytes activation." (PMID 18478076, 2008). "Second, NSCLC cases with AQP5-positive status displayed a higher rate of tumor recurrence than negative ones (54.7% vs. 35.1%, p = 0.005)." (PMID 18478076, 2008). "A few studies have suggested that AQP5 is involved in promoting epithelial-to-mesenchymal transition (EMT), a key step in cancer metastasis, and that transforming growth factor-β (TGF-β)-induced EMT modulates AQP3 expression supporting tumor invasion and the establishment of metastatic niches." (PMID 40305202, 2025). "Furthermore, CEACAM5 and AQP5 were significantly higher expressed in tumor-positive compared to tumor-negative lymph nodes and demonstrated particularly high T/N ratios, indicating their potential to detect metastatic lymph nodes for FGS and staging." (PMID 40379788, 2025). "Furthermore, the relationship between AQP3 and AQP5 and tumor invasiveness should not be overlooked." (PMID 39440058, 2024). "Interestingly, irrespective of CAP treatment, tumor organoids were expressing 2-fold less Aqp1, Aqp4, and 10-fold less Aqp3 levels than normal organoids, whereas Aqp5 expression was increased." (PMID 35169122, 2022). "Furthermore, AQP5 and AQP3 were suggested to be involved in proliferation and tumor transformation as a simultaneous overexpression was found to be correlated with an increased expression of EGFR, Ki-67, CK7, and a decrease of E-cadherin and increase of Vimentin." (PMID 33178018, 2020). "Knowing that AQP5 is also highly expressed in human tumors, we investigated AQP5 functional regulation and its ability to transport H2O2 that may account for a role in tumor progression." (PMID 31277235, 2019).
tumor (continued). "The results showed that in 60 tumor specimens, 19 (31.7%) patients showed high level of AQP5 expression, while 30 (50.0%) showed a moderate, intermediate level of staining, and 11 (18.3%) showed an absence of AQP5 staining, respectively." (PMID 25217331, 2014). "Only cancer cells, not tumor-infiltrating lymphocytes, showed AQP5 expression." (PMID 18478076, 2008). "Interestingly, AQP5 is often found phosphorylated in cancer as opposed to normal cells, indicating that AQP5 phosphorylation could be related to its role in tumor initiation and development." (PMID 39941100, 2025). "While Aqp5 mRNA expression was independent of its promoter methylation status in non-tumorigenic mouse mammary gland cells EpH4, studies using the most recent technologies to detect gene promoter methylation using genomic DNA from tumor cells arising from cancer patients showed divergent outcomes." (PMID 36768212, 2023). "According to the GEPIA database, AQP1, AQP3, AQP4, and AQP9 were significantly expressed in LUAD tissues compared to normal lung tissues (p < 0.05), but some genes including AQP0, AQP5, AQP6, AQP7, AQP8, AQP10, and AQP11 were not differentially expressed between tumor and normal tissues." (PMID 34708074, 2021). "Therefore, we suggested that AQP5 may play different roles in different cancer types with different mechanisms, and that in certain cancers may promote the proliferation of tumor cells and in certain cancers may inhibit the growth of tumor cells, but the specific mechanism is not clear." (PMID 33343628, 2020).